TMPRSS2 (transmembrane serine protease 2)
Diseases named in the same sentence as TMPRSS2 in open-access papers (continued):
Sharing a sentence is not in itself a finding about the gene and the disease.
infection (continued). "Each of these constructs also expressed human TMPRSS2, although we saw no enhancement to human ACE2 -mediated infection when TMPRSS2 was present (right)." (PMID 38768238, 2024). "A lack of productive infection of these cell types was concurrent with the low expression concentrations of ACE2, TMPRSS2, cathepsins B and L, and CD147." (PMID 37071849, 2023). "Although the PMs were not able to fully protect cell cultures from infection with authentic live SARS-CoV-2, dimer 10 exerted a minimal but detectable inhibition of SARS-CoV-2 entry in U87.ACE2+ and A549.ACE2.TMPRSS2+ cells." (PMID 37240111, 2023). "Together, our viral pseudoparticle infection assay and small molecule inhibitor data showed that Mv1Lu cells used endocytosis for SARS-CoV-2 entry, but not the TMPRSS2-based fusion pathway." (PMID 38033586, 2023). "Pre-treatment with SB extract and then infection with SARS-CoV-2 pseudovirus reduced infection in Calu-3 cells but not in VeroE6, suggesting that SB affects TMPRSS2, ultimately reducing virus entry." (PMID 37324739, 2023). "NRP1, used as a control, did not promote infection but it significantly increased viral entry when co-expressed with ACE2 or ACE2 and TMPRSS2, recapitulating previous observations." (PMID 35931765, 2022). "Although ACE2 and TMPRSS2 are not expressed in thyroid follicle cells, the possibility of ACE2- and TMPRSS2-independent infection cannot be excluded." (PMID 35625425, 2022). "Contrarily, Huh7 and 293FT strongly expressed TMPRSS2 but lacked ACE2 expression, indicating that each receptor has an individual role in aiding the infection." (PMID 33898942, 2021). "In the absence of TMPRSS2, NCOA7 inhibited infection by ~8-fold, however, in TMPRSS2 expressing cells the inhibitory effect dropped to ~3-fold." (PMID 34807954, 2021). "This specifically enhanced infection of SARS-CoV-2 PLVs, indicating that, in the absence of TMPRSS2 expression, much of the SARS-CoV-2 inoculum is not infectious in these cells." (PMID 33563656, 2021). "We showed that genetically engineered chicken DF-1 cells overexpressing both TMPRSS2 and ST3GAL1 support infection and replication of influenza virus in the absence of trypsin." (PMID 33413322, 2021). "Importantly, the inhibitory effect of apilimod was lost in the presence of TMPRSS2 (VAT cells), whereas the inhibitory effects displayed by remdesivir and EIDD-2801 were unaffected, suggesting that apilimod’s mode of action may be ineffective when TMPRSS2-dependent infection occurs." (PMID 33630831, 2021). "We identified TMPRSS2 and TMPRSS11D as TTSPs that facilitate infection by human and animal RVA strains in culture without trypsin supplementation." (PMID 33762412, 2021). "Although similar infection routes are known from other pathogens, no data on the protein expression and localization of ACE2 and TMPRSS2 is available in these areas of the human brain." (PMID 33122999, 2020). "In parallel, immunofluorescence assay was performed following the same protocol to identify the PEDV isolates (2013-A and NJ) propagated in Vero/TMPRSS2 and Vero/MSPL cells without trypsin, and in the Vero cells with or without trypsin at 48 h post-infection." (PMID 32471322, 2020). "Pair-wise comparisons showed that viral loads were significantly higher in WT compared to Tmprss2−/− mice after infection with PR8 and PR8_HA(MVEKT) at 2 and 4 days p.i. demonstrating that viral replication is strongly reduced in the absence of TMPRSS2." (PMID 30084768, 2018). "In conclusion, the quantitative organ distribution and sex dependence of ACE2 and TMPRSS2 levels may explain the primary airborne route for SARS-CoV-2 infection and lower infection rate in children but do not explain the more serious disease in elderly males." (PMID 40631549, 2025). "This could explain recent findings in HMC3 expressing relevant receptors i.e., ACE2, TMPRSS2, CD147, and NRP1, where no productive infection by some strains of SARS-CoV-2, but to Wuhan, Delta, and Omicron was reported." (PMID 39881814, 2024).
infection (continued). "However, in human lung and colon cells (primary sites of infection), SARS-CoV-2 is primarily activated by TMPRSS2, which does not require lysosomal activation and is not inhibited by chloroquine." (PMID 38675992, 2024). "It was further found that in HEK293T cells with almost no endogenous expression of ACE2 and NRP1, overexpression of NRP1 did not affect the infection degree of SARS-CoV-2 pseudovirus, but coexpression of NRP1, ACE2 and TMPRSS2 significantly promoted viral entry and infection." (PMID 37645223, 2023). "For instance, camostat alone at 10 μM was shown not to fully block infection in TMPRSS2+ Calu-3 cells, whereas the combination of 10 μM camostat with 10 μM EST, a broad inhibitor of cysteine proteases, could fully block the infection of SARS-CoV-1." (PMID 36985290, 2023). "To address this, we demonstrated that PK-15/TMPRSS2 #23 cells specifically enhanced the replications of IAV (H1N1) and SIV (H1N1) but not that of AKAV replication or lentiviral vector infection." (PMID 38251326, 2023). "In the absence of TMPRSS2, however, SARS-CoV-2 enters cells by ACE2-mediated endocytosis, undergoes proteolytic activation by cathepsin L in low-pH-containing endosomes, and fuses its membrane with a limiting endosomal membrane for infection." (PMID 34705560, 2022). "It is relevant to highlight that bromhexine has been initially identified as a potent inhibitor (IC50 = 0.75 μM) of the transmembrane serine protease 2 (TMPRSS2) of SARS-CoV, being involved also in the binding and infection (mainly via a nonendocytotic route) of SARS-CoV-2 to host cells." (PMID 36052135, 2022). "Unlike other cells, despite Huh-7 is permissive to SARS-CoV-2, co-expression analyses of ACE2 and TMPRSS2 revealed that Huh-7 cells strongly expressed TMPRSS2 but lacked ACE2 expression, which was understood as an indication that each receptor plays an individual role in aiding the infection." (PMID 36339347, 2022). "We found that the depletion of CTSL completely aborted the infection of pseudotyped SARS-CoV-2 S/HIV-1 viruses in CTSL+/TMPRSS2– HEK293T-hACE2high cells, whereas the depletion of TMPRSS2 did not abort the infection of pseudotyped SARS-CoV-2 S/HIV-1 viruses in the same cell line." (PMID 35572668, 2022). "We also found that TMPRSS2 and TMPRSS11D promote the infectious entry of immature RVA virions, but they could not activate nascent progeny virions in the late phase of infection." (PMID 33762412, 2021). "Additionally, compounds such as nafamostat mesylate, the TMPRSS2 inhibitor, active in Calu-3 but not active in HeLa-ACE2 cells had the potential to be active in advanced models of infection." (PMID 34083527, 2021). "Notably, A1AT was shown to inhibit the infection of H3N2 influenza A and influenza B viruses in a murine model, even though these viruses do not require TMPRSS2 priming, underscoring that A1AT can mediate anti-viral effects via multiple mechanisms." (PMID 33969249, 2021). "Also, the SARS-CoV-2 effector protease, transmembrane serine protease 2 (TMPRSS2), which is currently investigated for antiviral therapy, does not correlate with cellular infection." (PMID 33162939, 2020). "For instance, when 293T cells expressing human ACE2 but not TMPRSS2 were infected with SARS-CoV in the presence of 25 mM NH4Cl, which prevents endosomal acidification and hence blocks Cathepsin B/L, the extent of infection reduced ~40-fold over that in the absence of NH4Cl." (PMID 33290397, 2020). "After infection with a high dose of PR8M virus, processed HA1 as well as non-processed HA0 protein were detected in infected wild type mice whereas only HA0 protein was found in homozygous Tmprss2 mutant mice." (PMID 24348248, 2013). "Further, during infection of Calu-3 human airway cells, we found that MERS-CoV replication was highly dependent on TMPRSS2, whereas, to our surprise, SARS-CoV viral titers were only moderately reduced when catalytically active TMPRSS2 was not present in sufficient quantities." (PMID 39599912, 2024).
infection (continued). "Although cardiomyocytes express significant levels of ACE2, which serves as SARS-CoV-2 receptor, the lack of TMPRSS2, a cell-membrane-based protease needed for conformation changes in the spike protein of SARS-CoV-2 and cell membrane fusion, likely hampers direct cardiomyocyte infection." (PMID 36371548, 2023).
cancer (287 papers, 2006 to 2026). A tumor composed of atypical neoplastic, often pleomorphic cells that invade other tissues. "High TMPRSS2 expression levels associated with SARS-CoV-2 infection were also frequently found in various cancers." (PMID 40055791, 2025). "The interplay between ACE2, TMPRSS2, and immune cell infiltration is crucial for understanding cancer progression and susceptibility to SARS‐CoV‐2 infection." (PMID 40145441, 2025). "The TMPRSS2 expression in pan-tissues is associated with pathways involved in immune metabolism, cell growth as well as stromal and cancer signatures." (PMID 40055791, 2025). "Beyond its role in viral entry, TMPRSS2 is implicated in the biology of various cancers, particularly PCa." (PMID 40145441, 2025). "The intricate interplay between ACE2, TMPRSS2, and immune cell infiltration underscores the need for further research to elucidate their roles in cancer progression and susceptibility to SARS‐CoV‐2 infection." (PMID 40145441, 2025). "The reversal of all these expectable MTAP associations with tumor phenotype and patient outcome in cancers carrying an TMPRSS2:ERG fusion is the most striking finding of this study." (PMID 40554389, 2025). "In some cancers, such as prostate and rectal adenocarcinomas, TMPRSS2 is overexpressed and associated with better immune responses, and correlates with poor outcomes and enhanced tumor aggressiveness." (PMID 40145441, 2025). "In particular, viral proteins such as ACE2, FURIN, and TMPRSS2 are highly likely to be associated with cancer progression." (PMID 39350850, 2024). "The level of TMPRSS2 expression is tightly regulated in each tissue type, with over-expression of TMPRSS2 being associated with pathological states such as cancer." (PMID 38932275, 2024). "According to our study, variations in TMPRSS2 expression level influence prognosis across various cancers, and a higher level of TMPRSS2 associated with better prognosis in LUAD cohorts." (PMID 36992839, 2023). "The most probable mechanism that has been proposed for the role of ERG in cancer is linked to the formation of gene fusion of TMPRSS2 and ERG." (PMID 37762215, 2023). "According to the results of this study, the overexpression of TMPRSS2:ERG was associated with the aberrant expression of the genes that enhance osteomimicry of cancer cells, facilitating their invasion and growth in bone tissue." (PMID 37511059, 2023). "TMPRSS2 genetic variants are related to increased susceptibility to disease and for risk factors such as cancer." (PMID 37237997, 2023). "Its general expression is cancer unspecific, however in PCa a decrease in expression is linked to the TMPRSS2::ERG fusion." (PMID 37349736, 2023). "We further explored the potential signalling mechanism and pathway linked with TMPRSS2 in four common types of cancers (breast, lung, colorectal and ovarian) through the R2 platform and Reactome tool." (PMID 34951103, 2022). "Here our study reported a germline-somatic association of TMPRSS2-ERG with this cross-cancer locus of 17q12/HNF1B, mechanistically and biologically implicating PCa risk and progression." (PMID 36443337, 2022). "In this study, we exploited the cBioPortal database to study the mutations of TMPRSS2 in different cancers, including the mutation site, type, amino acid changes, and the corresponding three-dimensional structure of the protein." (PMID 35281819, 2022). "The multi‐omics analysis also revealed the significance of TMPRSS2 expression and possible cascades associated with TMPRSS2 in several kinds of cancers (human) and progression of COVID‐19." (PMID 34951103, 2022). "Pan-cancer mutation prognosis analysis showed that ACE1 and TMPRSS2 mutations were associated with better survival in cancer patients (p = 0.0273 and 1.18e−10), whereas mutated SLC6A19 was associated poor survival in cancer patients (p = 1.47e−4)." (PMID 34458283, 2021).
cancer (continued). "According to data from TCGA and Genotype-Tissue Expression (GTE), ACE2 and TMPRSS2 were found to be potentially implicated in the genetic susceptibility to SARS-COV-2 among cancer patients." (PMID 34399734, 2021). "It is important to predict the prostate's susceptibility to SARS‐CoV‐2 infection in cancer patients and the disease outcome by assessing TMPRSS2 expression in cancer tissues." (PMID 33609069, 2021). "High cytoplasmic and nuclear YAP1 were both significantly linked to cancers with TMPRSS2:ERG rearrangement and ERG expression." (PMID 32488048, 2020). "We found that there were three cancer types were closely associated with TMPRSS2 and two types with IFITM3." (PMID 33061814, 2020). "The patient group with the highest level of PDE4D7 expression (i.e., PDE4D7 scores 4-5) showed lowest risk of disease progression after surgery in the TMPRSS2-ERG fusion positive cancers." (PMID 31275657, 2019). "High GGH expression was linked to the TMPRSS2:ERG-fusion positive subset of cancers (p < 0.0001), advanced pathological tumor stage, and high Gleason grade (p < 0.0001 each)." (PMID 28146062, 2017). "Commonly found with a TMPRSS2:ERG fusion, the concurrent loss of PTEN contributes to a poor prognosis in cancer in the presence of an existing TMPRSS2:ERG fusion with an increased risk of recurrence." (PMID 24018887, 2013). "Several early cohort studies suggest that the presence of the TMPRSS2:ERG fusion product is associated with relatively poor cancer-specific survival." (PMID 18781147, 2008). "Despite the lack of characterisation of the individual proteins, the phenotypic features of the TMPRSS2:ERG-associated cancers, as a class, have been described." (PMID 18781147, 2008). "Beyond infectious diseases, TMPRSS2 has also been linked to some cancers, suggesting it could be a valuable target for drug development." (PMID 39858469, 2025). "Inhibitors targeting TMPRSS2 could potentially reduce SARS‐CoV‐2 infectivity; however, their use must be balanced against the risk of promoting tumor progression in cancers where TMPRSS2 acts as a suppressor." (PMID 40145441, 2025). "When considering the most significantly enhanced cancer-associated biological processes in the LAPCa category within the TMPRSS2-ERG molecular subtype, such signaling pathways as the “cAMP signaling pathway” and the “TGF-beta signaling pathway” come to the fore." (PMID 37298233, 2023). "The enzymatic activity of TMPRSS2 has also been implicated in cancer invasion." (PMID 37511059, 2023). "Since the expression of TMPRSS2 in cancers is diverse, we wondered whether TMPRSS2 is associated with tumor prognosis." (PMID 35558557, 2022). "Furin mutations mostly increased expression of ACE2 and TMPRSS2 in various cancers, indicating furin mutations might facilitate COVID-19 cell entry in cancer patients." (PMID 35682644, 2022). "TMPRSS2 expression, mutation, and prognostics in pan-cancers are unclear." (PMID 36364238, 2022). "Moreover, the gene expression signatures shared between SPOP mutation and TMPRSS2-ERG fusion cancers consisted largely of genes expressed in normal prostate tissue." (PMID 34066106, 2021). "Indeed, chromosomal proximity was recently suggested to underlie the cancer-prone translocation TMPRSS2-ERG." (PMID 20617169, 2010). "Therefore, the analyses may provide the potential value of TMPRSS2 expression for the survival of patients associated with cancer, and give potential direction to prevent COVID‐19 pandemic for specific tumour patients." (PMID 34951103, 2022). "Besides, a high level of TMPRSS2 was linked with immune cell infiltration in various cancers." (PMID 34951103, 2022). "TMPRSS2 mutations may be a prognostic marker for long survival rates in pan-cancers." (PMID 36364238, 2022).
cancer (continued). "Hence, the underlined results may help to explore TMPRSS2 as an effective biomarker and therapeutic target for many kinds of cancer in humans, and also provide directions for the prevention of COVID‐19 pandemic for particular tumour patients." (PMID 34951103, 2022). "Hence, 27 predicted genes and proteins associated with TMPRSS2 might have a role in regulating cancer development (mediated by TMPRSS2) and prognosis." (PMID 34951103, 2022). "Interestingly, the series of above molecular events also occurs in cancer patients, such as a cytokine storm is observed in cancer, ACE2 and TMPRSS2 expression is found higher in cancer patients, and coagulopathy is a potential risk observed in a number of cancer patients." (PMID 33912588, 2021). "Hence, the changes in ACE2 and TMPRSS2 messenger RNA (mRNA) expression caused by cancer or SARS-CoV-2 might compromise its protective role and accelerate disease progression." (PMID 34131396, 2021). "This study was designed to systematically locate the regions of differential expression of these genes in single cross-sections of five cancerous prostates and evaluate whether the location of the carcinoma was associated with TMPRSS2-ERG or PCA3 mRNA levels or ERG protein expression." (PMID 26294063, 2015). "Additionally, we have recently demonstrated that loss of 5′-ERG sequences coupled with duplication of TMPRSS2:ERG fusion sequences predicts extremely poor cancer-specific survival independently of Gleason score and PSA level at diagnosis in a conservatively managed watchful waiting patient cohort." (PMID 18594527, 2008). "TMPRSS2 is involved in carcinogenesis of prostatic cancer, promoting cancer cell invasion and metastasis by stimulating epithelial-to-mesenchymal signaling, degradation of the ECM, and fusion with the oncogenic transcription factor ERG." (PMID 40631549, 2025). "During pathophysiological conditions, the TMPRSS2 expression levels and their prognostic value highly varied across different cancer types." (PMID 40055791, 2025). "Collectively, these studies highlight the complex role of TMPRSS2 in cancer biology and its interaction with SARS‐CoV‐2 infection." (PMID 40145441, 2025). "Given that this association strengthened with disease severity, coupled with the fact that Caco-2/TC7 cells are a cancer-derived cell line, it can be postulated that there is a potential association between SGLT1 and TMPRSS2 in pathological conditions." (PMID 40227199, 2025). "Analyses of TCGA datasets showed a heterogeneous expression of TMPRSS2 across different cancer types." (PMID 40055791, 2025). "The upregulation of ACE2 by TMPRSS2 in cancer cells and PBMNCs highlights a significant overlap between cancer biology and infectious diseases, particularly in the context of the COVID-19 pandemic." (PMID 40055791, 2025). "It was suggested that TMPRSS2, as a member of a pericellular proteolytic cascade, induces cancer cell invasion, tumor growth, and metastasis." (PMID 41408854, 2025). "The expression levels and effects of ACE2 and TMPRSS2 were significantly different in different cancer types." (PMID 40145441, 2025). "Our data indicates that TMPRSS2high cells, which have increased PD-L1 expression, responded to nivolumab, demonstrating a TMPRSS2-dependent response along with increased immune cell infiltration into cancer cells." (PMID 40055791, 2025). "Protein network analysis identified 27 protein partners of TMPRSS2, suggesting its involvement in regulating cancer progression." (PMID 40145441, 2025). "TMPRSS2 expression varies across different cancer types, influencing tumor progression, immune infiltration, and patient prognosis." (PMID 40145441, 2025). "This review investigates the dual roles of angiotensin‐converting enzyme 2 (ACE2) and transmembrane serine protease 2 (TMPRSS2) in SARS‐CoV‐2 infection among cancer patients." (PMID 40145441, 2025).